IL6 (interleukin 6)
Diseases named in the same sentence as IL6 in open-access papers (continued):
Sharing a sentence is not in itself a finding about the gene and the disease.
diabetes (continued). "This is in line with a recent report describing the deficient production of TNF-α, IL-6, and MCP-1 in response to different Mycobacterium species by MFs isolated from mice with diabetes." (PMID 29513874, 2018). "We observed a significant decrease in the levels of TNF-α, IFN-γ, IL-12, and IL-6 in the baseline plasma samples from individuals with T2DM indicating a systemic downregulation in the cytokine levels among uncontrolled diabetes." (PMID 30258443, 2018). "In general, concentric and isometric torques were lower and tumor necrosis factor (TNF)-α, interleukin (IL)-6, and IL-1β plasma levels were higher in the groups with diabetes than in controls." (PMID 30043856, 2018). "Epidemiological evidence suggests that inflammatory markers, such as TNF-α and IL-6, predict the development of diabetes and glucose disorders." (PMID 30914847, 2018). "Our group found that through NF-κB inhibition, P. hepiali suppressed the release of proinflammatory cytokines, including tumor necrosis factor alpha, IL-2, IL-6 and IL-10, in a rat model of diabetes induced by a high-fat diet and STZ." (PMID 28662169, 2017). "Diabetes induces a significant increase of IL-1β and IL-6 expression of Kupffer cells in Ins2Akita mice." (PMID 28493939, 2017). "It is described in the literature that IL-6 rises with increasing age and in the presence of comorbidities, such as cardiovascular diseases, diabetes, arteriosclerosis, and coronary heart illnesses." (PMID 28376092, 2017). "IL-6 was correlated with PI for deciduous teeth (Pearson correlation, r=0.922, p=0.003) in patients with diabetes." (PMID 28403363, 2017). "Carboxymethyl lysine, interleukin-6, and immunoglobulins were also increased as a result of diabetes." (PMID 28298934, 2017). "existence of diabetes mellitus, age 2: 50 years, IL-18 2 804.3 pg/ml, IL-6 2 3.92 pg/ml, and IL-1B 2 0.86 pg/ml." (PMID 28474577, 2017). "STZ administration induces hyperglycemia and increases MDA and IL-6 in soleus muscle, toxic intermediates in the development of oxidative stress and inflammation in diabetes." (PMID 28808475, 2017). "Joint effects between genetic variations of FTO, IL-6, HSPD1 genes and diabetes on breast cancer risk." (PMID 28591216, 2017). "Among many inspected relationships, we found a correlation between Treg counts and diabetes stabilization determined by HbA1c levels, the presence of diabetic neuropathy, lipid spectra, BMI, and IL-6 levels." (PMID 28553653, 2017). "Added to these, a direct relationship has been established between increased cytokines, such as tumour necrosis factor-α (TNF-α), interleukin 6 (IL-6) and interleukin 10 (IL-10) and excessive hyperglycaemia in both types 1 and 2 diabetes." (PMID 28974040, 2017). "Key words:Melatonin, periodontal disease, diabetes mellitus, interleukin-1β, interleukin-6, prostaglandin E2." (PMID 29075409, 2017). "These evidences would help in interpreting the interaction between diabetes and IL-6 rs1800796 shown in the present study." (PMID 28591216, 2017). "Multivariate survival analysis of breast cancer associated with genetic variations of FTO, IL-6, HSPD1 genes and diabetes." (PMID 28591216, 2017). "Definition of factors, existence of diabetes mellitus, age 2 50 years, IL-18 2 804.3 pg/ml, IL-6 2 3.92 pg/ml, IL-1B 2 0.86 pg/ml, and averaging albumin level < 3.8 gm/dl within the first year of PD." (PMID 28474577, 2017). "This study has two major findings: (i) Higher baseline levels of hsCRP, IL-6 and IL-1Ra showed associations with larger increases in HR and decreases in several HRV indices after initial adjustment for age, sex and diabetes status." (PMID 29195493, 2017). "The mortality of PD patients was increased while they had increasing numbers of predictive factors including titers of IL-18 ≧ 804.3 pg/ml, titers of IL-6 ≧ 3.92 pg/ml, titers of IL-1ß ≧ 0.86 pg/ml, age ≧ 50 years-old, and diabetes." (PMID 28474577, 2017).
diabetes (continued). "In this study, IL-18, TNF- α and IL-6 had positive correlation with the degree of diabetes control and is similar to what had been observed in other studies." (PMID 28577020, 2017). "Patients with diabetes and periodontal disease had significantly higher mean levels of IL-1β, IL-6 and PGE2 than healthy subjects." (PMID 29075409, 2017). "IL-6 is a typical inflammatory cytokine that stimulates inflammation and autoimmune responses in many diseases, including diabetes, Alzheimer’s disease, and some tumors." (PMID 28842424, 2017). "Multivariate odds ratio of breast cancer risk associated with genetic variations of FTO, IL-6, HSPD1 genes and diabetes." (PMID 28591216, 2017). "In both wild-type and Nrf2-KO mice, diabetes increased the expression of IL-6 and NF-κB compared to control group, respectively." (PMID 28373900, 2017). "The increase of immunoglobulins (IgG, IgA, and IgM) as a result of diabetes in the current study is consistent with the increase in IL-6 and other findings revealed a positive correlation between these parameters." (PMID 28298934, 2017). "Diabetes mellitus, age ≧ 50 years, IL-18 ≧ 804.3 pg/ml, IL-6 ≧ 3.92 pg/ml, IL-1ß ≧ 0.86 pg/ml, and average levels of albumin <3.8 gm/dl." (PMID 28474577, 2017). "We further analyzed the joint effects of FTO, IL-6, HSPD1 polymorphisms with diabetes on breast cancer risk." (PMID 28591216, 2017). "IL-6 is known to stimulate the inflammatory and auto-immune processes in many diseases, such as diabetes or atherosclerosis." (PMID 27106358, 2016). "A study demonstrates that management of diabetes with morin reduced the elevation of inflammatory cytokines IL-1β, IL-6 and TNF-α via a SphK1/S1P signaling pathway." (PMID 27527213, 2016). "In patients suffering from diabetes, IL-6 secretion was lower, and the turnover of E-selectin was more intensified than in the patients without diabetes." (PMID 27834825, 2016). "Risk factors for cardiovascular disease with a pro-inflammatory component include LDL cholesterol, smoking, elevated blood sugar, hypertension, diabetes, infections, oxidant damage, interleukin-6 (IL-6) and C-reactive protein (CRP)." (PMID 27070643, 2016). "When multiple regression models were used, diabetes remained significantly associated with NETs, nucleosomes, HNE-DNA complexes, IL-6 and TNFα after adjustment for BMI." (PMID 28005949, 2016). "Compared with IS individuals, all IR (IR + type 2 diabetes mellitus) individuals exhibited a significant reduction in plasma leptin and adiponectin, but had increased IL-6 levels." (PMID 27342408, 2016). "Another candidate for the Nrf2 function downstream of the IL-6/IL-1 repression is diabetes prevention." (PMID 27211851, 2016). "Genotypic frequencies and association of the IL6-174 SNP with presence of plaques, increased IMT, and degree of stenosis (adjusted for gender, age, hypertension, diabetes, and smoking habits)." (PMID 27662210, 2016). "Our data indicated possible interplay between homocysteine and IL-6 during diabetes thus influencing NETosis." (PMID 27811985, 2016). "For example, an EP4 agonist exacerbated renal fibrosis in streptozotocin-diabetic mice and enhanced diabetes-induced expression of inflammatory cytokines, including IL-6." (PMID 27351842, 2016). "The inflammatory process in diabetes is associated with the secretion of inflammatory cytokines by endothelial cells, e.g., tumor necrosis factor-alpha (TNF-α) and interleukin 6 (IL-6)." (PMID 26861982, 2016). "Elevated levels of plasma CRP have been reported to enhance the development of diabetes by interacting with cytokines (IL-6 and TNF-α) in stimulating the acute phase inflammatory response." (PMID 27379252, 2016). "In agreement we also found that diabetes associated increase in renal cortical TGF beta, RAGE, IL-6, IL-18, matrix metalloproteases (MMPs, MMP2 and 9) mRNA expression were prevented in treated groups." (PMID 27901066, 2016).
diabetes (continued). "What’s more, ZER significantly (p < 0.05) ameliorated diabetes-induced upregulation of tumor necrosis factor-α, interleukin (IL)-1 and IL-6." (PMID 27463726, 2016). "In population-based studies, such as the Multi-Ethnic Study of Atherosclerosis, Atherosclerosis Risk in Communities and West of Scotland Coronary Prevention Study (WOSCOPS), inflammatory markers (e.g. IL-6, CRP), are strongly associated with diabetes risk." (PMID 27666719, 2016). "Compared with IS-derived cultures, all IR (IR + type 2 diabetes mellitus) SC-derived cultures secreted higher levels of IL-6 (3.4 ± 3.1 vs 6.8 ± 1.8 ng/ml, respectively)." (PMID 27342408, 2016). "Elevated markers of inflammation such as C-reactive protein or interleukin-6 have been detected in children and adults with diabetes, supporting the notion that diabetes represents a condition of chronic inflammation." (PMID 26911143, 2016). "We observed that plasma IL-6 levels were nearly fivefold elevated in diabetes subjects (251.0 ± 25.65 pg/ml) when compared to healthy subjects (56.40 ± 8.87 pg/ml)." (PMID 27811985, 2016). "While the evidence supports a role of IL6 methylation with regard to both, air pollution and diabetes, the relevance of hyper- versus hypomethylation and the association with the IL6 SNPs studied here needs further clarification." (PMID 26911440, 2016). "In this study, we for the first time evaluated the role of IL-6 in cardiac remodeling 12 weeks after diabetes induction in mice." (PMID 26972749, 2016). "Epidemiological studies have demonstrated that increased levels of mediators of inflammation and acute-phase reactants, such as fibrinogen, C-reactive protein (CRP), and IL-6, correlate with the incidence of type 2 diabetes mellitus (T2DM)." (PMID 27070352, 2016). "Subjects with AF showed higher IL-6 concentrations; a pattern between higher levels of the cytokine and age, diabetes, AS, CHA2DS2-VASc score, anti-gout therapy and a poor SPPB performance also emerged." (PMID 27568019, 2016). "We have previously shown that diabetes is associated with increased production of PGE2, IL-6 and TNF-α in macrophages." (PMID 27351842, 2016). "A recent meta-analysis confirms the consistent dose-response relationships between IL-6, CRP and diabetes risk." (PMID 27666719, 2016). "Increased systemic IL-6 in diabetes is well known and we have shown that IL-6 is a potent inducer of NETs13." (PMID 27811985, 2016). "It seems plausible that in addition to these genes, Nrf2-mediated inhibition of IL-6/IL-1 induction contributes to the prevention and improvement of diabetes." (PMID 27211851, 2016). "Circulating markers of inflammation include C-reactive protein (CRP), interleukin-6 (IL-6), fibrinogen, and tumor necrosis factor-alpha (TNF-α), some of which have been associated with cognitive dysfunction in people with diabetes." (PMID 26060511, 2015). "IL-6 was demonstrated to correct peripheral nerve dysfunction in experimental diabetes in rats through correction of vascular endothelium dysfunction and increase of nerve blood flow via a mechanism that involves endothelium-derived hyperpolarizing factor." (PMID 25961054, 2015). "Key words:Melatonin, periodontal disease, diabetes mellitus, interleukin-6, tumor necrosis factor-alpha, C-reactive protein, inflammatory markers." (PMID 26644840, 2015). "It was found that HDL-c is an independent predictor for IL-6 (p = 0.02) and sVCAM-1 (p < 0.03) after correcting for age, gender,ethnicity, smoking status, hypertension, diabetes, central obesity, TC, TG and LDL-c." (PMID 25614985, 2015). "Circulating IL-6 is increased in some autoimmune and chronic inflammatory diseases, such as diabetes, arthritis, Grave’s disease and atherosclerosis." (PMID 26075620, 2015). "A surge in pro-inflammatory markers, Il-6 and TNF-α, has been associated with type 2 diabetes mellitus (T2DM)." (PMID 26391589, 2015).
diabetes (continued). "Serum levels of TNF-α and IL-6 were measured by enzyme-linked immunosorbent assay and CRP by nephelometry by using the proper commercial kits in 30 patients with diabetes and periodontal disease, and also in a control group of 30 healthy subjects." (PMID 26644840, 2015). "STZ diabetes in G2 rats showed also an increase in lipid peroxidation and IL-6 and decreased catalase, SOD, and GSH activity in the serum and the kidney tissue homogenate compared with that of the negative control group." (PMID 25629046, 2015). "We aimed to detect changes in cerebrospinal fluid biomarkers such as amyloid β42, phosphorylated tau protein, interleukin 6, and acetylcholine in diabetic rats over time, and to analyse the relationship between diabetes and cognitive impairment." (PMID 26271247, 2015). "No changes in plasma levels of OPN, IL-10, TNFα, IL-12p70, IL-1β, IL-6, and KC were observed in response to diabetes or NFAT inhibition; however plasma IFN-γ was reduced in diabetic animals that had been treated with A-285222." (PMID 25918731, 2015). "(1990), who suggested a role for IL6 in the process of B-cell suppression and destruction during the course of insulin-dependent diabetes mellitus." (PMID 26216433, 2015). "A recent meta-analysis of perspective studies identified the two inflammatory markers IL-6 and C-reactive protein (CRP) as significantly associated with diabetes, with an increased risk of 26% associated with elevated CRP, and 31% due to elevated IL-6 levels." (PMID 26783955, 2015). "In diabetes, oxidative stress increases the excretion of inflammation-related cytokines, such as IL-6 and TNF-α." (PMID 26176625, 2015). "In diabetes, IL-6 was reported as an independent predictor of microvascular complications and cardiovascular disease." (PMID 25298619, 2014). "Diabetes is considered as a kind of inflammatory and metabolic diseases, so the overproduction of IL-6, TNF-α, and IL-1β has been observed in people with diabetes." (PMID 24995360, 2014). "Chronic inflammation indicated by an elevated C-reactive protein or interleukin-6 plays a critical role in the development of diabetes." (PMID 24504072, 2014). "In the current study, the reduced LPS-stimulated MCP-1 and IL-6 expression in the diabetic macrophages provided a mechanistic link between impaired mononuclear phagocyte function and diabetes-induced exacerbation of ischemic injury." (PMID 24886035, 2014). "To compare adipocyte populations from different mouse models of diabetes for their ability to release inflammatory mediators, we investigated the accumulation of KC, IL-6, and MCP-1 in cultures of (pre-)adipocytes derived from C57BL/6J, NOD, and NZO mice." (PMID 24672802, 2014). "In the diabetes panel, in addition to IL-6, the GLP-1 concentration was found to be higher in patients without a fistula, whereas the GIP level was observed at significantly higher concentrations in the fistula group." (PMID 25120588, 2014). "Cytokines such as IL-6, IL-1β, and TNF-α are known for their involvement in the process of bone loss in diabetes." (PMID 24803925, 2014). "The transcription and expression of inflammatory factors, including TNF-α and IL-6, are activated in patients with type 2 diabetes mellitus." (PMID 25187806, 2014). "One important observation in this study was that A-285222 treatment for 4 weeks significantly reduced the diabetes-driven IL-6 levels in plasma as well as mRNA expression in the aortic arch." (PMID 23755169, 2014). "This work confirms previous studies demonstrating diabetes-induced reductions in peripheral nerve tissue of cytokines such as IL-6, TNFα and CNTF." (PMID 24152426, 2013). "Significantly elevated IL-6 levels were detected in the serum of rheumatoid arthritis, diabetes, acute pancreatitis, HIV, and cancer patients." (PMID 23853724, 2013).
diabetes (continued). "Of interest is that IL-6 has emerged as an important cytokine with a link to atherosclerosis and diabetes, and evidence from two large genetic studies indicates causality between IL-6 receptor signalling and CAD." (PMID 23987834, 2013). "The aim of this study was to determine the correlation between pneumonia and the levels of C-reactive protein (CRP) and interleukin-6 (IL-6), as well as to identify early predictors of pneumonia in acute ischemic stroke patients with diabetes mellitus." (PMID 23935729, 2013). "Major periodontal risk factors were recorded (age, gender, diabetes and smoking status), as well as plasma levels of inflammatory markers (CRP, orosomucoid, IL-6) and adipokines (adiponectin, leptin)." (PMID 23526947, 2013). "Our previous studies demonstrated that IL-6 and adhesion molecules are important factors in mediating angiotensin as well as diabetes-induced retinal vascular injury." (PMID 23437353, 2013). "Urinary F2-isoprostanes are positively associated with circulating pro-inflammatory cytokines, such as monocyte chemoattractant protein-1 (MCP-1) and interleukin-6 (IL-6), which are predictors of diabetes and CVD." (PMID 23698776, 2013). "In contrast, elevated levels of serum IL-6 were found in patients suffering from type 2 diabetes and natural gingivitis compared to patients with diabetes and healthy gingival conditions." (PMID 23408963, 2013). "In this study, mRNA levels of IL-1β, IL-6 and ICAM-1 were increased in the retinas of type 2 diabetic rats after 2 months of diabetes supporting the notion that chronic inflammation underlies the vascular pathology in type 2 diabetes." (PMID 23383097, 2013). "Serum IL-6 also increases in chronic inflammations, including viral diseases and bacterial infections, autoimmune diseases, ischemia, and diabetes." (PMID 23554823, 2013). "Several mutual proinflammatory cytokines and adipocytokines also act on the pathogenesis of autonomic neuropathy and diabetes, such as interleukin 6, C-reactive protein, leptin and adiponectin." (PMID 23424665, 2013). "In the retina, it was shown that diabetes activates induction of proinflammatory mediators such as monocyte chemoattractant protein-1, interleukin-6, intercellular adhesion molecule-1, inducible nitric oxide synthase, matrix metalloproteinase-9, and TNF-alpha." (PMID 24259948, 2013). "The elevated levels of IL-6 were found in autoimmune and chronic inflammatory diseases such as rheumatoid arthritis, inflammatory bowel diseases, diabetes, multiple sclerosis, and asthma." (PMID 23533301, 2013). "It has been reported that activation of TLR3 in PBMCs of patients with diabetes can increase the expression of IL-6." (PMID 23946637, 2013). "The renal expression of inflammatory cytokines such as TNF-α, IL-6 and IL-1β were demonstrated to increase in diabetes, contributing to the development of DN." (PMID 24499158, 2013). "Elevation of TNF-alpha and IL-6 was detected in diabetes, which was related to the progression of diabetic complications." (PMID 23853776, 2013). "Several studies have shown that subclinical systemic inflammation, as measured by elevated levels of CRP and IL-6, predicts the development of diabetes." (PMID 23690772, 2013). "Age, male, diabetes, hypertension, history of CKD, hyperuricemia, and interleukin-6 levels (≥7.54 ng/L) were independent risk factors for reduced eGFR." (PMID 23951003, 2013). "Previously, various studies have documented that diabetes enhanced the production of inflammatory mediators such as iNOS, IL6, and TNF-α in the retina." (PMID 23671886, 2013). "Kolaviron prevented diabetes induced increase in the hepatic levels of proinflammatory cytokines; interleukin (IL)-1beta, IL-6, tumour necrosis factor (TNF-α) and monocyte chemotactic protein (MCP-1)." (PMID 24359406, 2013).